BDNF (brain derived neurotrophic factor)
Diseases named in the same sentence as BDNF in open-access papers (continued):
Sharing a sentence is not in itself a finding about the gene and the disease.
Parkinson disease (continued). "In addition, using an animal model of Parkinson’s disease (PD), which is also one of the most common neurodegenerative diseases, the upregulation of BDNF and an increase in neurogenesis following exercise was demonstrated." (PMID 36983803, 2023). "BDNF seems to serve as a trophic factor for mesencephalic dopaminergic neurons by increasing their survival, including survival of the neuronal cells that degenerate in Parkinson’s disease." (PMID 37239153, 2023). "BDNF has even been suggested as a promising therapeutic agent for Parkinson’s disease." (PMID 37239153, 2023). "Of interest, considering that decreased levels of BDNF are associated with neurodegenerative diseases, including Alzheimer’s and Parkinson’s diseases, the observation that FA can increase BDNF expression holds promise for the prevention and treatment of these conditions." (PMID 37569576, 2023). "However, the exact role of BDNF in improving neuroplasticity and cognition in different disease states, such as Parkinson’s disease, still remains inconclusive." (PMID 36801969, 2023). "Moreover, as a novel drug for the treatment of Parkinson's disease, naringin activates antiapoptotic programs by inducing the production of neurotrophic substances such as BDNF and vascular endothelial growth factor." (PMID 36865741, 2023). "Although the association between reduced BDNF levels and CNS pathologies is not necessarily causal, reduced BDNF levels are linked to increased neuronal impairment and degeneration, as observed in Parkinson’s disease patients." (PMID 35955546, 2022). "A recent meta-analysis found that exercise training, regardless of type (aerobic vs. resistance), volume (≥150 min/week vs. <150 min/week), and length (≥12 weeks vs. <12 weeks), significantly increased plasma BDNF levels in people with Parkinson's disease and multiple sclerosis." (PMID 36451805, 2022). "Also, STG improved memory deficits in Parkinson's disease rats via upregulation of the BDNF expression." (PMID 35265716, 2022). "However, none of the participants suffered from endocrine diseases with altered cortisol production or neurodegenerative diseases (Alzheimer's, Parkinson's, or Huntington's disease) with known changes in cortisol and BDNF levels." (PMID 35250657, 2022). "Additionally, we have demonstrated that Nano-BDNF PEG-PLE presents clear benefits over unformulated BDNF in the treatment of Parkinson’s disease and ischemic stroke models in mice while preserving BDNF’s circulation and residence in affected areas." (PMID 35890287, 2022). "Therefore, in this section, we will discuss cardiovascular dysfunction related to NGF- or BDNF-compromised brain diseases, such as AD or Parkinson’s disease (PD)." (PMID 34827728, 2021). "These properties, combined with the increase in BDNF expression, suggest that E. umbellata extracts may be effective in the treatment of neuro-inflammatory disorders, such as Alzheimer’s or Parkinson’s diseases." (PMID 33552740, 2021). "Therefore, we decided to utilize BDNF AT liposomes for efficacy studies in 6-OHDA rat model of Parkinson’s disease." (PMID 33953687, 2021). "The pathogenesis of AD and Parkinson’s disease involve neuroinflammatory activities, oxidative stress, mitochondrial dysfunction, and dysfunction in brain-derived neurotrophic factor." (PMID 33013406, 2020). "Interestingly, there is already abundant data showing a role for BDNF/TrkB signaling in the etiology of Parkinson's disease, at least from in vivo animal models." (PMID 31429825, 2019). "It is well known that exercise often leads to an increase of BDNF in the brain and in the peripheral circulation, and that this improves health outcomes in patients with neurodegenerative diseases such as Parkinson’s." (PMID 31509546, 2019). "Our BDNF results are in line with prior human research in a variety of psychiatric conditions, and a recent review of neurotrophic factors in animal models of exercise and Parkinson’s disease." (PMID 29568518, 2018).
Parkinson disease (continued). "Similarly, studies have shown a decrease of BDNF in vulnerable brain areas, such as the substantia nigra in Parkinson’s patients." (PMID 30223579, 2018). "Thus, BDNF level in blood represents a marker of cognitive dysfunction and progress of neurodegeneration in AD and other neurodegenerative diseases such as Parkinson’s disease and vascular dementia." (PMID 28289378, 2017). "Accumulated evidence supports the constructive role of the CREB/BDNF pathway in enhancing memory and cognition, and disturbance of phosphorylated CREB/BDNF levels in the hippocampal region leading to the progression of neurodegenerative diseases such as Alzheimer’s and Parkinson’s." (PMID 28792471, 2017). "Due to their dopaminergic character, SH-SY5Y cells are generally considered as a model for Parkinson’s disease, however, they can be differentiated to dominantly cholinergic phenotype suitable for AD studies by treatment with retinoic acid (RA) and brain-derived neurotrophic factor (BDNF)." (PMID 29065138, 2017). "In Parkinson’s disease (PD), the significant reduction of BDNF and TrkB in the substantia nigra (SN) might contribute to the death of DA neurons thus worsening the neurodegeneration." (PMID 26198255, 2015). "BDNF has been demonstrated to promote motor neuron survival and motor axon growth, therefore has been studied in a variety of neurodegenerative conditions, including Parkinson's disease and ALS." (PMID 25334047, 2014). "Additionally, in the CNS, pretreatment of dopaminergic neuronal progenitors in a Parkinson's disease model with perlecan‐conjugated laminin E8 fragments resulted in enhanced maturation and neurite extension of progenitor cells through activation of BDNF–TrkB and GDNF–RET signaling." (PMID 41555564, 2026). "Further markers of NMJ stability, notably brain-derived neurotrophic factor (BDNF), and glial cell line-derived neurotrophic factor (GDNF) have been assessed and a reduction in the levels of both have been associated with muscle loss and sarcopenia in Parkinson’s disease patients." (PMID 40772803, 2025). "In addition, how exercise-like lifestyle changes keep maintaining the BDNF response or activating its receptors throughout life can have a potential impact on ameliorating neurodegenerative diseases like Alzheimer’s or Parkinson’s disease, which requires further understanding." (PMID 39194500, 2024). "Additionally, these dopaminergic neurons displayed heightened sensitivity to the neurotoxin MPTP, indicating that impaired BDNF–TrkB signaling may play a role in the progression of Parkinson’s disease." (PMID 39935805, 2024). "Recent investigations have shown that plasma EVs contain BDNF and the level and biochemical properties of BDNF are potential biomarkers for conditions such as walking speed decline in older adults and disturbance-related motor symptoms in patients with Parkinson’s disease." (PMID 39697631, 2024). "Additionally, patients with Parkinson’s disease exhibited significantly lower serum BDNF levels." (PMID 39935805, 2024). "Given that SHED stem cells, when cultured in vitro with trophic factors such as EGF and bFGF, express proneural genes (Ngn2 and Mash1) or dopaminergic neuron-like markers (dSHED) by BDNF (brain-derived neurotrophic factor), treatment could promote beneficial effects in Parkinson’s." (PMID 37631323, 2023). "Brain-derived neurotrophic factor (BDNF), which is known to regulate neuronal survival and function in the central nervous system, plays an important role in the treatment of neurodegenerative diseases and has been associated with Parkinson's, Alzheimer's, and Huntington's diseases." (PMID 34589504, 2021). "Although the changes in TrkB isoform expression in SN regions and its effect on Parkinson’s disease are therefore not fully understood, TrkB.FL and/or TrkB.T1 may be a potential drug target, as BDNF is neuroprotective and may be beneficial for Parkinson’s disease." (PMID 32403409, 2020).
Parkinson disease (continued). "Thus, the protective effects of treadmill exercises for 3 weeks, 5 days a week, may increase BDNF gene expression in the brain leading to disease improvement through inhibition of inflammatory pathways that are involved in Parkinson’s disease." (PMID 32489563, 2020). "Animal models of exercise and Parkinson’s disease (PD) have found that the physiologic use of exercise may interact with the neurodegenerative disease process, likely mediated by brain derived neurotrophic factor (BDNF)." (PMID 29568518, 2018). "Since BDNF is critical to the support and maintenance of neuronal populations, thus promoting healthy cognitive abilities, it is suggested that exercise can be protective in attenuating age-related cellular damage in diseases like Alzheimer's and Parkinson's disease." (PMID 26992232, 2016). "In addition, decreased BDNF levels may result in decreased hippocampal neurogenesis; BDNF expression is decreased in patients with AD and Parkinson’s disease." (PMID 27919226, 2016). "This BDNF gene therapy might be helpful in the early stage of Parkinson’s disease." (PMID 26198255, 2015). "Improving overall cell survival might therefore also potentially increase the survival of pre-differentiated cells, but as in Parkinson’s disease additional survival factors (e.g. BDNF, GDNF) might be required to ensure the long-term survival and integration of these neurons." (PMID 22876937, 2012). "Both in vitro and in vivo studies corroborate that PF offers protection against Parkinson’s disease models induced by MPP+ and MPTP, through the stimulation of the PI3K/AKT and BDNF/CREB pathways." (PMID 40650274, 2025). "The next topic to research will be the BDNF/CREB and PI3K/AKT modulation effects of PF’s protection against Parkinson’s disease, and, in particular, the determination of the expression levels of proteins such as AKT, P-PI3K, and AKT2." (PMID 40650274, 2025). "BDNF, GNDF, and TGF‐ß3 are preferred as GFs because they are effective in dopaminergic neuron differentiation, which is particularly lost in Parkinson's patients." (PMID 40904189, 2025). "Notably, experimental Parkinson’s disease models indicate potential neuroprotective effects of Toxoplasma gondii infection, including improved motor function, reduced catalepsy, altered nociception, enhanced oxidative balance, and elevated striatal dopamine and brain-derived neurotrophic factor." (PMID 41049318, 2025). "For example, in MPTP-induced Parkinsonism, HDAC inhibitors enhanced the expression of GDNF (glial cell-derived neurotrophic factor) and BDNF (brain-derived neurotrophic factor) in astrocytes." (PMID 39057675, 2024). "It highlighted its role in reducing neuronal inflammation and apoptosis while enhancing BDNF/GDNF-related and dopaminergic signaling pathways in the nigrostriatum of Parkinson’s disease animal models." (PMID 39844853, 2024). "Serum growth factors (BDNF, FGF-21, NGF and proNGF), α-synuclein, physical performance and Parkinson’s Disease Fatigue Scale (PFS-16) responses were analyzed to evaluate the pre-post variation and differences among groups." (PMID 36845654, 2023). "Supplementation of BDNF has been shown to protect synapses against various toxic insults in neurodegenerative diseases, including AD, Huntington’s disease, ALS, and Parkinson’s disease in animal models." (PMID 36720792, 2023). "Neurotrophic factors, such as BDNF and GDNF, are well-known regulators of the dopamine system and are described as candidates for treating Parkinson’s disease as they exhibit dual neuroprotective and neurogenic properties." (PMID 35431833, 2022). "Mechanistically, it was found that the protective effects of FTY in Parkinson’s disease were correlated with the activation of survival pathway mediated by Akt/ERK1/2 and increased expression of a neuron-specific brain-derived neurotrophic factor (BDNF)." (PMID 34831161, 2021).
Parkinson disease (continued). "Fluoxetine, imipramine, and milnacipran upregulated BDNF and GDNF in the striatum and substantia nigra of rats in the MPTP model of Parkinson’s disease." (PMID 33802323, 2021). "Nevertheless, no significant cognitive nor quality-of-life improvements are observed in people with Parkinson’s disease after HIIT, while it is effective in improving serum BDNF and other functional outcomes." (PMID 33809413, 2021). "Supportively, previous evidence showed that treadmill training increased brain-derived neurotrophic factor (BDNF), which activated neural mitochondrial complex I in Parkinson’s disease." (PMID 34440215, 2021). "This study proves that DA5‐CH can increase the expression of GDNF and BDNF in midbrain tissue, and provide a new direction for the study of the therapeutic mechanism of new GLP‐1/GIP dual agonists for Parkinson's disease." (PMID 34125470, 2021). "It has also been shown that human ADSCs significantly enhanced expression of brain-derived neurotrophic factor (BDNF) and improved motor lost function in the 6-OHDA murine Parkinson’s disease model, suggesting a pro-healing effect." (PMID 32194404, 2020). "BDNF and GDNF were studied therapeutically in models of Parkinson disease (PD) and Huntington disease (HD), with loss of neurons that express TrkB and RET." (PMID 31244606, 2019). "In a subsequent study, they assessed the relationship between brain-derived neurotrophic factor (BDNF) and the n-3 PUFA-mediated neuroprotective effect using the same animal model of parkinsonism." (PMID 30233293, 2018). "The present results have demonstrated for the first time that astrocytes exhibit an endogenous self-repairing mechanism via release of BDNF and/or GDNF during very early stages of rat Parkinsonism of 6-OHDA-leisoned rats." (PMID 23251488, 2012). "Our findings are impelling to explore inverse regulation of BDNF and SNCA genes by GFI1 and MEF2 in neurons generally and in Parkinson's disease models in particular." (PMID 19737418, 2009). "Recent clinical studies have demonstrated that BDNF levels are significantly reduced in the substantia nigra and striatum of Parkinson’s disease patients, correlating with both motor impairment and non-motor symptoms." (PMID 41199384, 2025). "The outcome measures included assessment of Movement Disorder Society Unified Parkinson's Disease Rating Scale (MDS-UPDRS) and serum levels of tumor necrosis factor-alpha (TNF-α), malondialdehyde (MDA), brain-derived neurotrophic factor (BDNF), and α-synuclein (α-Syn)." (PMID 40434674, 2025). "Reduced BDNF levels have also been shown in patients with Parkinson’s disease with restless legs syndrome (RLS) compared to those with Parkinson’s disease without RLS." (PMID 38337587, 2024). "In this work, we characterized a cell model of Parkinson’s disease based on SH-SY5Y neuroblastoma cells with stable alpha-synuclein overexpression, which were differentiated towards dopaminergic neuronal phenotype by sequential addition of RA + BDNF." (PMID 38203538, 2023). "Some studies have shown that neurotrophic factors such as glial cell-derived neurotrophic factor (GDNF) and brain-derived neurotrophic factor (BDNF) upregulate tyrosine hydroxylase (TH), improve movement disorders and provide neuroprotection in animal models of Parkinson’s disease." (PMID 35557834, 2022). "Another study revealed that brain-derived neurotrophic factor (BDNF)-induced chronic activation of D3 receptors improved motor functions and increased the dendritic spines in the striatal neurons of 6-hydroxydopamine (6-OHDA)-induced Parkinson’s rat." (PMID 34943913, 2021). "BDNF mimetics are well tolerated in mammalian models, demonstrate efficacy in rodent models of Alzheimer’s, Parkinson’s and Huntington’s disease and no adverse outcomes are reported for humans consuming 7,8 dihydroxyflavone as a nootropic supplement." (PMID 28900183, 2017).
Parkinson disease (continued). "Also, the results of Western blot and immunofluorescence staining of BDNF indicate that pVAX-BDNF complexed with RDP can be delivered into brain, and show neuroprotective properties in experimental Parkinson’s disease (PD) model." (PMID 23555734, 2013). "It is concluded that BDNF‐PLGA‐NPs, GDNF‐PLGA‐NPs, and TGF‐ß3‐PLGA‐NPs are promising brain drug delivery carriers for NSC inducers, which could be useful in developing strategies for Parkinson's disease management, particularly when targeted with TRF." (PMID 40904189, 2025). "BDNF may also serve as a link between neurodegenerative and inflammatory processes in ocular diseases, as shown in uveoretinitis mouse models, which may partly explain the elevated prevalence of DED in Parkinson’s disease, where BDNF signalling is impaired." (PMID 41226736, 2025). "Similar morphological changes in MSNs are observed in animal models of parkinsonism, probably due to the reduction in the delivery of BDNF by nigral neurons since the striatal neurons do not express neurotrophin but rather through nigral neurons and transported to the striatum." (PMID 38419644, 2024). "However, in an MTPT mouse model of Parkinson’s disease, fingolimod did not increase BDNF sustainably." (PMID 35250559, 2022). "The primary purpose of this study was to investigate the immediate and long-term effects of Nordic Walking (NW) exercise on walking function, motor/non-motor Parkinson's Disease (PD) symptoms, and serum brain-derived neurotrophic factor (BDNF) in persons with idiopathic PD." (PMID 36311206, 2022). "Moreover, nigral dopaminergic neurons degenerate in the absence of BDNF, suggesting its participation in the pathogenesis of Parkinson's disease." (PMID 33269104, 2020). "Healthy rats given the combinational treatment, with the implant being applied to target the striatum (BDNF) and sustantia nigra (GDNF) with the hope of assisting transplant survival and long-term axon extension, respectively, in future work with animal models of Parkinson’s disease." (PMID 31427916, 2019). "In a rodent model of Parkinson’s disease, viral vector transfer of BDNF and GDNF into nigrostriatal neurons was no more potent than GDNF alone, implying that current striatal changes in GDNF alone may underlie MWM sex differences." (PMID 30356904, 2018). "To date, the potential beneficial effect of neurotrophins, NGF and BDNF, in particular, have been explored in light of several neurodegenerative disorders, including but not limited to AD, Amyotrophic lateral sclerosis (ALS), Huntington disease, Parkinson’s Disease and even obesity." (PMID 23210531, 2012). "Moreover, BDNF is of particular therapeutic interest because of its neurotrophic actions on neuronal populations involved in several neurodegenerative diseases, including peripheral sensory neuropathies; amyotrophic lateral sclerosis (ALS); Parkinson's disease (PD) and Alzheimer's disease (AD)." (PMID 20644624, 2010). "This is supported by a recent finding of an increase in striatal proBDNF and not mature BDNF in the 6-hydroxydopamine model of Parkinson’s disease with improvement in motor function following treatment with the neuroprotective compound, Diphenyl diselenide." (PMID 28813484, 2017).